RNU6-466P (RNA, U6 small nuclear 466, pseudogene)
Gene: Small nuclear RNA gene on chromosome 15 (30,956,248 to 30,956,350, reverse strand). Ensembl gene ENSG00000212526.
Homologues: Orthologues: chimpanzee U6 (100% identical), macaque U6 (90% identical), dog U6 (78% identical), mouse Gm22345 (69% identical). Paralogues in human: RNU6-1145P (82% identical), RNU6-1175P (81% identical), RNU6-1316P (81% identical), RNU6-1323P (81% identical), RNU6-38P (81% identical), RNU6-116P (80% identical), RNU6-188P (80% identical), RNU6-29P (80% identical), RNU6-310P (80% identical), RNU6-393P (80% identical), RNU6-39P (80% identical), RNU6-621P (80% identical), and 1286 more.